RNU2-9P (RNA, U2 small nuclear 9, pseudogene)
Gene: Small nuclear RNA gene on chromosome 2 (148,825,691 to 148,825,835, reverse strand). Ensembl gene ENSG00000222126.
Homologues: Orthologues: chimpanzee U2 (99% identical), macaque U2 (91% identical), pig U2 (77% identical), mouse Gm25259 (71% identical), guinea pig U2 (63% identical), zebrafish U2 (48% identical), dog U2 (32% identical), pig U2 (32% identical), dog U2 (31% identical), rat LOC120096843 (31% identical), rabbit U2 (21% identical). Paralogues in human: RNU2-68P (81% identical), RNU2-59P (77% identical), U2 (74% identical), RNU2-36P (74% identical), RNU2-48P (74% identical), RNU2-2 (73% identical), RNU2-4P (73% identical), RNU2-64P (73% identical), RNU2-6P (73% identical), RNU2-61P (72% identical), RNU2-14P (72% identical), RNU2-23P (72% identical), and 64 more.